ATG5 (autophagy related 5)
Diseases named in the same sentence as ATG5 in open-access papers (continued):
Sharing a sentence is not in itself a finding about the gene and the disease.
seminoma (3 papers, 2023). A radiosensitive malignant germ cell tumor found in the testis (especially undescended), and extragonadal sites (anterior mediastinum and pineal gland). "The use of autophagy inhibitor 3-methyladenine (3-MA) and knockdown of ATG5 could overcome the cisplatin resistance in seminoma." (PMID 37264402, 2023). "In the seminoma of H. sapiens, upregulation of METTL3 can increase the m6A level of ATG5 transcript, which increases the expression of ATG548." (PMID 37210465, 2023). "In seminoma 54, METTL3 could increase autophagy by modulating ATG5, thus promoting cisplatin resistance." (PMID 36632456, 2023).
triple-negative breast carcinoma (3 papers, 2018 to 2022). An invasive breast carcinoma which is negative for expression of estrogen receptor (ER), progesterone receptor (PR), and human epidermal growth factor receptor 2 (HER2). "In earlier studies by Yousefi and co-workers, silencing of ATG5 in cultured human HeLa cervical or MDA-MA-231 triple negative breast cancer cells, with short interfering RNA (siRNA), rendered these cells more resistant to staurosporine or doxorubicin for several days and delayed cell death." (PMID 29494533, 2018).
vitiligo (3 papers, 2021 to 2022). Generalized well circumscribed patches of leukoderma that are generally distributed over symmetric body locations and is due to autoimmune destruction of melanocytes. "In response to oxidative stress, vitiligo melanocytes also display a reduced gene expression of ATG5 and ATG12, whose lower levels are caused by a deficiency in the expression of their transcription factor HSF-1." (PMID 36230960, 2022). "To investigate the possible involvement of autophagy in vitiligo, we initially determined the relative mRNA abundance of some Atg transcripts (Atg5, Atg7, Atg8) by quantitative reverse-transcriptase PCR." (PMID 33767135, 2021). "The expression levels of Atg7 and Atg8 were significantly higher in non-lesional vitiligo melanocytes (VHMs) than in control cells (NHMs), while the level of Atg5 showed a tendency to increase, although this was not statistically significant." (PMID 33767135, 2021). "We demonstrated that, although Atg5 and Atg8 mRNAs were not upmodulated, vitiligo fibroblasts showed a tendency to exhibit elevated autophagy, as assessed by increases of Atg7 gene expression, LC3, and Beclin I production concurrently with the down-modulation of SQSTM1/p62." (PMID 33767135, 2021).
adenomyosis (2 papers, 2022 to 2024). The growth of endometrial tissue inside the muscular wall of the uterine corpus. "KLF4 overexpression increases the autophagy level of hESCs by transcriptionally promoting ATG5 expression, and abnormally decreased KLF4 in adenomyosis impairs hESC decidualization by repressing autophagy." (PMID 35761172, 2022).
age (2 papers, 2017 to 2020). A temporal measurement of the time period elapsed since an identifiable point in the life cycle of an organism. "The enhancement of p62 in an autophagy-deficient lens by the defect of Atg5 was found to result in age-related cataract." (PMID 32186721, 2020). "The loss of lens-specific autophagy-related 5 (Atg5) has been reported to result in age-related cataract formation, and Pik3c3/Vps34 genes are shown to leading cortical cataract in lens." (PMID 28083623, 2017).
airway hyperresponsiveness (2 papers, 2012 to 2025). "We focused on autophagy-related 5 gene (ATG5) and autophagy-related 7 gene (ATG7) because ATG5 is essential for autophagosome formation, and ATG7 has been previously shown to be associated with airway hyperresponsiveness in animal models." (PMID 22536318, 2012).
allergic disease (2 papers, 2022). An immune response that occurs following re-exposure to an innocuous antigen, and that requires the presence of existing antibodies against that antigen. "We assessed the mediation effect of this SNP, located in the ATG5 (Autophagy Related 5) gene, on the allergic disease through DNA methylation and found that 75.7% of the effect of rs9372120 on the allergic disease was mediated by DNA methylation of cg20372759." (PMID 36456559, 2022).
amyloidosis (2 papers, 2017 to 2022). A disorder characterized by the localized or diffuse accumulation of amyloid protein in various anatomic sites. "The expression levels of Atg5 were not significantly different among any of the groups, and the levels of Hspa5 were upregulated in the amyloidosis-induced group without CR treatment (AL+F) but repressed by CR treatment (CR+F)." (PMID 28225824, 2017).
anaemia (2 papers, 2019 to 2023). "Furthermore, Atg5 autophagy-deficient mice develop anemia and extramedullary hematopoiesis (EMH), most likely due to the absence of proinflammatory cytokines." (PMID 37180758, 2023). "Similarly, mice with HSC-specific ablation of Fip200 and Atg5 have shown significant reduction in HSCs, increased ROS and HSC proliferation, decreased HSC reconstitution ability in the bone marrow, and survival defects including severe anemia and lymphopenia." (PMID 37180758, 2023).
aneurysm (2 papers, 2019 to 2021). Bulging or ballooning in an area of an artery secondary to arterial wall weakening. "It would be interesting to postulate whether cell‐specific removal of key autophagy factors, such as ATG5, ATG6 or ATG12, would result in a phenotype unique to aneurysm disease." (PMID 31025534, 2019). "On the other hand, mRNA expression of LC3, ATG5, Beclin-1, and ATG7 tended to increase in aneurysm samples, although in a nonsignificant manner." (PMID 34754985, 2021).
Anxiety (2 papers, 2025 to 2026). Intense feelings of nervousness, tension, or panic often arise in response to interpersonal stresses. "Lastly, to determine whether autophagy-deficient PVALB neurons impact anxiety-like behaviors, we tested control and Pvalb-atg5 mice in three anxiety tests: 1) the elevated plus maze, 2) the light/dark box, and 3) the open field test." (PMID 41353607, 2026). "However, Atg7 knockdown in the Fos-dependent robust activity marking ensemble promoted memory generalization, while knockdown of Atg5 or Atg7 in the Npas4-dependent robust activity marking ensemble increased anxiety levels." (PMID 40536998, 2025). "By contrast, anxiety was not impaired in Pvalb-atg5 animals, which is not surprising given the complex role of PVALB interneurons in anxiety, involving multiple brain areas and networks." (PMID 41353607, 2026).
Arthritis (2 papers, 2022). Inflammation of a joint. "WJR significantly reduced toe swelling, arthritis scores, and expression of miRNA-146a and autophagy genes (ATG5, ATG7, ATG12, Beclin1, LC32, and Bcl2)." (PMID 36440364, 2022). "We noted that treatment of the rat model with WJR resulted in a significant reduction in toe swelling, arthritis severity, expression of miRNA-146a, and expression of autophagy genes (ATG5, ATG7, ATG12, Beclin1, LC32, and Bcl2)." (PMID 36440364, 2022). "IL-21 induces the expression of Beclin-1, autophagy-related 5 (Atg5), and LC3-phosphatidylethanolamine conjugate 3-II (LC3-II) through the inhibition of C/EBP homologous protein (CHOP) in FLS from rats with adjuvant-induced arthritis." (PMID 35844494, 2022).
brain tumor (2 papers, 2018 to 2021). "Moreover, it has been documented to block autophagy through the CREB3/ATG5 pathway in brain tumor." (PMID 34276768, 2021).
Burkitt lymphoma (2 papers, 2018 to 2019). A rare form of malignant mature B-cell non-Hodgkin lymphoma. "Formerly known as apoptosis specific protein (ASP), ATG5 was first identified in Burkitt's lymphoma apoptotic cells." (PMID 30386331, 2018).
cervical squamous cell carcinoma (2 papers, 2021 to 2022). A squamous cell carcinoma arising from the cervical epithelium. "For patients with cervical squamous cell carcinoma, patients with ATG5 overexpression have significantly shorter OS than the ATG5 down-expression group." (PMID 34901004, 2021).
chronic pancreatitis (2 papers, 2020 to 2025). A chronic inflammatory process causing damage and fibrosis of the pancreatic parenchyma. "Perhaps the most intriguing findings in this study are the acinar cell–specific Atg5 or TFEB KO mice developed severe pancreatic changes reminiscent of chronic pancreatitis in the Lieber-DeCarli control diet–fed mice regardless of alcohol feeding." (PMID 31987928, 2020).
co-infection (2 papers, 2012 to 2015). "In the presence of M. tuberculosis co-infection, ATG5 silencing reduced the 1,25D3 mediated inhibition of HIV at day 7 from 91% to 4% (P<0.001)." (PMID 22589721, 2012). "In the absence of M. tuberculosis co-infection, ATG5 RNAi completely abrogated the 1,25D3 mediated inhibition of HIV by day 7 (P<0.001)." (PMID 22589721, 2012).
colon adenocarcinoma (2 papers, 2020 to 2024). "In colon adenocarcinoma (COAD), similar with SKCM, there was also an inverse-relationship between Sec23a and Atg5 expression and the TNM stages and overall survivals." (PMID 32811814, 2020). "We analyzed the correlation between KRAS mutational status and expression of several autophagy genes, including MAP1LC3B, ATG5, ATG10, ATG13, and ATG14 in both COAD (colon adenocarcinoma) READ (rectum adenocarcinoma) as well as normal tissue." (PMID 39057088, 2024).
colorectal tumor (2 papers, 2015 to 2018). "Macroscopically, colorectal tumors presented in the middle and distal colon both in Atg5-deficient mice and Ctr mice." (PMID 26496833, 2015). "Atg5 also exhibited global positive staining in the colorectal tumor cell cytoplasm." (PMID 26496833, 2015). "As expected, Atg5 exhibited negative staining throughout the majority of the colorectal tumor cell in Atg5-deficient mice." (PMID 26496833, 2015).
coronary artery disease (2 papers, 2019 to 2023). "We finally identified ATG5, TOMM20, MFN2 transcriptionally differed between MI and stable coronary artery diseases." (PMID 37304955, 2023).
cyst (2 papers, 2025). A sac-like closed membranous structure that may be empty or contain fluid or amorphous material. "In the ADPKD zebrafish model, atg5-KO inhibits autophagy to promote cyst formation, whereas the use of BECN1 peptide can activate autophagy to improve cyst formation." (PMID 40851276, 2025). "In ARPKD kidney organoids, overexpressing autophagy-related 5 (ATG5) or knocking out the primary cilia-associated gene kinesin family member 3 A (KIF3A) activates autophagy and suppresses cyst formation, with cilia ablation accompanied by upregulated autophagy." (PMID 41359105, 2025).
cytomegalovirus infection (2 papers, 2019 to 2021). A herpesvirus infection caused by Cytomegalovirus. "Since ATG5 and BECN1 are enriched with purified virions, we wanted to know whether they accumulated during HCMV infection." (PMID 30872707, 2019).
dry eye (2 papers, 2017 to 2021). "For this reason, we evaluated the diagnostic performance of tear autophagy related 5 (ATG5) for discriminating SS DE and compared it with other dry eye parameters included in diagnostic criteria of SS (Schirmer I and OSS)." (PMID 33406739, 2021). "The diagnostic performances of tear ATG5 and dry eye parameter tests were compared with a receiver operating characteristic (ROC) curve." (PMID 33406739, 2021). "The immunostaining of conjunctival epithelium showed a punctate pattern of ATG5 and LC3B-II in SS dry eye." (PMID 29222450, 2017). "We previously identified that autophagy related 5 (ATG5) was elevated in the tear and conjunctival epithelial cells of SS dry eyes (DE) compared to non-SS DE." (PMID 33406739, 2021). "ATG5 levels in tears and the conjunctival epithelium strongly correlated with ocular staining scores, and one month of topical corticosteroid treatment reduced both ATG5 and LC3B-II/I levels in tear film and the conjunctival epithelium of patients with SS dry eye." (PMID 29222450, 2017). "In tears, ATG5 and LC3B-II/I levels were significantly higher in SS dry eye." (PMID 29222450, 2017). "ATG5 and LC3B-II mRNA in the conjunctiva were also elevated in SS dry eye compared with non-SS dry eye." (PMID 29222450, 2017).
dysplasia (2 papers, 2016 to 2019). A usually neoplastic transformation of the cell, associated with altered architectural tissue patterns. "On follow-up, within H. pylori-eradicated group, Atg5 expression increased sequentially from control to dysplasia and cancer subgroups." (PMID 30742638, 2019). "Within the H. pylori-positive group, a statistically significant trend was observed in the levels of Atg5 increasing sequentially from control to dysplasia, and to cancer subgroups (each P < 0.05)." (PMID 30742638, 2019). "Similarly, Atg5 expression increased sequentially from control to dysplasia, and to cancer subgroups within the H. pylori-positive group." (PMID 30742638, 2019). "While Atg9a KO mice did not display obvious skeletal dysplasia, they were significantly smaller than newborn wild-type mice and Atg5 KO mice." (PMID 27811852, 2016).
endometriosis (2 papers, 2016 to 2023). The growth of functional endometrial tissue in anatomic sites outside the uterine body. "It was found that FTO-dependent m6A regulates the progression of endometriosis via the ATG5/PKM2 Axis." (PMID 37840133, 2023). "Specifically, we found that transcript levels of beclin-1, ATG5, ATG4B, and ATG2B were significantly decreased in endometriotic lesions compared with uterine horns (from endometriosis-induced mice treated with PBS)." (PMID 26775710, 2016).
Gait ataxia (2 papers, 2024 to 2025). A type of ataxia characterized by the impairment of the ability to coordinate the movements required for normal walking. "Taken together, our data show that conditional loss of ATG5 in mice induces a progressive gait ataxia, manifested by an increase in footslips and disturbed gait kinematics." (PMID 39815080, 2025). "To investigate whether the conditional deletion of ATG5 in mice leads to gait ataxia through PC loss, we evaluated their motor performance by examining the ability to traverse beams of varying widths: wide (25 mm), regular (12 mm) and narrow (5 mm) beams." (PMID 39815080, 2025). "Clinical phenotypes associated with congenital deficiencies in autophagy genes ATG7, ATG5 and SQSTM 1 further support the selective vulnerability of PCs, particularly in gait ataxias." (PMID 39367235, 2024).
glaucoma (2 papers, 2014 to 2021). Increased pressure in the eyeball due to obstruction of the outflow of aqueous humor. "However, baicalin treatment attenuated the EIOP-induced increase in protein expression of LC3-II, Beclin-1, and ATG5 in Model+NS group, which indicated that baicalin inhibited autophagy in glaucoma progression." (PMID 34860641, 2021). "As here, they demonstrated up-regulation of Atg5 and increases in LC3-II and concluded that enhanced autophagy is likely highly relevant in milder situations of axonal damage such as glaucoma." (PMID 25444463, 2014).
Glucose intolerance (2 papers, 2022). Glucose intolerance (GI) can be defined as dysglycemia that comprises both prediabetes and diabetes. "When compared to control mice, Atg5-deficient CD11c+ mice exhibit increased glucose intolerance and decreased insulin sensitivity when fed HFD." (PMID 35301333, 2022). "ATG5 might play a crucial role in the production and secretion of insulin in pancreatic β cells, and deletion of ATG5 results impaired insulin secretion and glucose intolerance." (PMID 36313818, 2022).
hearing loss (2 papers, 2022). "Besides, a previous study also showed that the deficiency of ATG5 leads to the degeneration of HCs and severe congenital hearing loss, indicating that autophagy plays a cytoprotective function in the cochlea." (PMID 35686233, 2022). "Among these genes, ATG5, ATG7 showed the highest node scores in the mild hearing loss group, whereas MTOR, BECN1 showed the highest node scores in the severe hearing loss group." (PMID 35463035, 2022).
herpesvirus infection (2 papers, 2024). "One of the most common methodologies employed to analyze autophagy in herpesvirus infection is the silencing of the autophagy-related gene ATG5, due to the ATG5 protein is essential for autophagosome formation." (PMID 38915300, 2024). "Additionally, myeloid-specific knockout of several autophagy genes (RB1CC1, Beclin1, ATG3, ATG5, ATG7, ATG14, or ATG16L) in animals subjected to herpesvirus infection results in elevated inflammation and prevented viral reactivation from latency." (PMID 38447109, 2024).
injury (2 papers, 2017 to 2024). Damage inflicted on the body as the direct or indirect result of an external force, with or without disruption of structural continuity. "However, it is still unknown if the decreased ATG5 level was due to the feedback inhibition of autophagy activity or not, because previous studies showed that autophagy activity was increased in the acute phase of neonatal brain injury." (PMID 29326554, 2017). "In this study, we found that the HuR protein expression was inducible in the mouse model of APAP‐induced liver injury and found that HuR could protect against APAP‐induced liver injury by promoting the expression of NRF2, cyclin A1, cyclin B1, cyclin D1, CDK2, ATG3, ATG5 and ATG7." (PMID 39614424, 2024).
leishmaniasis (2 papers, 2019 to 2023). Infectious disease that is transmitted through the bite of hematophagous female phlebotomine sand flies. "Taken together, these data indicate that regardless of the species and individual variations, the presence of LRV in New-World Leishmania influences inflammasome activation by a TLR3/TRIF/IFN-β/ATG5 axis, which is critical for the outcome of Leishmaniasis." (PMID 31754185, 2019).
Listeria infection (2 papers, 2012 to 2022). "Similar experiments show increased sensitivity to Listeria infection when mice lack atg5 in myeloid cells, again suggesting a protective role for autophagy." (PMID 36288298, 2022). "Atg5 silencing increases intracellular growth of Listeria and decreases survival of flies, showing that in flies autophagy plays a protective role during Listeria infection." (PMID 36288298, 2022).
liver failure (2 papers, 2021). A liver disease characterized by the liver losing or has lost all of its function. "In D-gal/LPS-induced liver failure, loss of ATG5 significantly increased IL-1β expression, with massive infiltration of neutrophils and aggravated liver failure." (PMID 34930917, 2021). "Inactivation of autophagy by atg5 knockdown or bafilomycin treatment partially rescued early lethality with liver failure." (PMID 33863987, 2021).
lung squamous cell carcinoma (2 papers, 2021 to 2024). "This study aims at assessing the function of ATG5-induced autophagy in progression of lung squamous cell carcinoma and its upstream mechanism." (PMID 34253689, 2021). "Mimic miR-30a-5p suppresses ATG5-mediated autophagy in lung squamous cell carcinoma cells." (PMID 34253689, 2021).
lysosomal storage disorders (2 papers, 2017 to 2025). "These insights into ATG5’s multifaceted functions could pave the way for novel therapeutic strategies targeting lysosomal dysfunction, including lysosomal storage disorders and chronic inflammatory diseases." (PMID 39936034, 2025).
malignant mesothelioma (2 papers, 2023 to 2025). A malignant neoplasm of the pleura or peritoneum, arising from mesothelial cells. "ATG5 has been detected in serum and proposed as an early biomarker of malignant mesothelioma, with an elevated level associated with activated autophagy." (PMID 41294712, 2025).
malnutrition (2 papers, 2021 to 2024). Inadequate nutrition resulting from poor diet, malabsorption, or abnormal nutrient distribution. "ATG3, ATG5, ATG7, or ATG16L1 deficiency in mice leads to malnutrition and energy expenditure, leading to death shortly after birth." (PMID 33854691, 2021). "The effect of malnutrition on autophagic machinery and mitochondrial quality control in LPS-challenged BM neutrophils, where we found higher PINK1 and lower ATG5 and p62, remains to be explored further and may independently drive neutrophil activation and pathology." (PMID 39028622, 2024).